SNORD8 (small nucleolar RNA, C/D box 8)
Synonyms: mgU6-53; RNU6C
Gene: Small nucleolar RNA gene on chromosome 14 (21,397,292 to 21,397,401, reverse strand). Ensembl gene ENSG00000200785.
Gene Ontology:
Biological process: RNA processing
Cellular component: nucleolus
Homologues: Orthologues: chimpanzee SNORD8 (100% identical), macaque SNORD8 (100% identical), rabbit SNORD8 (96% identical), guinea pig SNORD8 (95% identical), rat Snord8 (93% identical), mouse Snord8 (90% identical), pig SNORD8 (89% identical). Paralogues in human: SNORD9 (72% identical).